TNF (tumor necrosis factor)
Diseases named in the same sentence as TNF in open-access papers (continued):
Sharing a sentence is not in itself a finding about the gene and the disease.
parasitemia (continued). "After infection with P. berghei ANKA, compared to MC-deficient WBB6F1-W/Wv mice, the control littermate WBB6F1+/+ C57BL/6 mice had lower parasitemia and mortality with higher tumor necrosis factor (TNF) levels." (PMID 28428784, 2017). "Infection of C57Bl/6 mice by pleomorphic African trypanosomes Trypanosoma brucei and T. congolense is characterized by parasitemia waves coupled with the production of systemic levels of TNF." (PMID 28733685, 2017). "The parasitemia/response rate of each parameter was greater in patients suffering P. vivax or P. ovale malaria than P. falciparum; regarding parasitemia, TNF-α response was stronger in P. vivax or P. ovale infection than P. falciparum." (PMID 28243235, 2017). "Proinflammatory cytokine production, such as IL-12, IFN-γ and TNF-α, are required to activate T lymphocytes, macrophages and other cells, resulting in parasitemia control." (PMID 29255475, 2017). "TNF is able to decrease intracellular parasitemia, involving calcium as a second messenger of the pathway." (PMID 27080559, 2016). "Data indicate invasion reduction in the presence of 1 and 2 ng/ml TNF treatment with parasitemia being 13.11% (± 5.98 n = 8) and 12.72% (± 9.4 n = 7) lower than untreated control samples." (PMID 27080559, 2016). "Here, we identify a novel pathway of TNF regulation by IL-10 from Tr1 cells during parasitic infection." (PMID 26765224, 2016). "Our findings identify Blimp-1-dependent IL-10 produced by Tr1 cells as a critical regulator of IFNγ-dependent, TNF-mediated tissue damage in the spleen in parasitic infections." (PMID 26765224, 2016). "Parasites where incubated with TNF (1, 2 or 8 ng/ml at a final parasitemia of around 4% (3.98 a.u. ± 0.21, n = 9)." (PMID 27080559, 2016). "Coinciding in IFNγR-/- mice, reduced amounts of pro-inflammatory cytokines IL-15 and TNFα were observed at the time of peak parasitemia (day 6)." (PMID 26070118, 2015). "This study shows that deficiency in Ly49E expression results in lower parasitemia at the early stage of P. berghei ANKA infection, i.e. at days 6–7 p.i., which correlates with lower IFN-γ and TNF-α expression in liver NK cells." (PMID 24498110, 2014). "We found that parasite infection promotes the production of theinflammatory cytokine TNFα in the host macrophage." (PMID 28357238, 2014). "TNF levels closely correlate with the temperature of patients during paroxysms and with parasitemia as well." (PMID 24741587, 2014). "Corroborating the critical role of TNF-α for host defense, Tc-TNF-R1−/− mice revealed increased parasitemia, accelerated death and more augmented TNF-α, IL-1 and IL-6 concentrations in circulation." (PMID 23717489, 2013). "Secretion of proinflammatory Th1-type cytokines such as interferon-γ, interleukin-12 and tumor necrosis factor-α prevents parasitemia and development of chronic disease." (PMID 23497385, 2013). "After 24 h of parasite infection, murine J774 cells produced detectable amounts of TNF-α (34±5 pg/ml) that were strikingly raised (640±35 pg/ml, P<0.001) by adding recombinant mouse MIF (1 μg/ml)." (PMID 23451183, 2013). "We then followed the kinetics of the CD8 epitope-specific cells by 2 distinct assays, i.e., in vivo cytotoxicity and ex vivo surface mobilization of CD107a and ICS for IFN-γ and TNF-α, after s.c. parasite infection or i.m. immunization with AdASP-2 vaccine." (PMID 22615561, 2012). "The decreased huRBC chimerism and parasitemia seen in NSG mice correlated with the release of TNFα and IL-12p70." (PMID 21483851, 2011). "This Consensus has advised that when a fungal or parasitic infection occurs, TNF-α blockers must be withdrawn." (PMID 22567476, 2011). "Among cytokines, TNF-α plays a critical role in host defense against intracellular parasite infections." (PMID 21526166, 2011).
parasitemia (continued). "In the serum of PcAS-infected mice, TNF levels are very high around peak parasitemia, so it is possible that a TNF-modulated reduction in CXCL12 production in the bone marrow is contributing to the observed impaired B lymphopoiesis." (PMID 21687602, 2011). "Accordingly, T. brucei infected MyD88 KO mice and IFN-γ KO mice exhibited reduced Tip-DC percentage and reduced production of TNF, correlating with an inability to efficiently control parasitemia." (PMID 20714353, 2010). "Our studies demonstrated that TLR4 signaling is required for optimal production of IFN-γ, TNF-α and nitric oxide (NO) in the spleen of infected animals and, as a consequence, Tlr4−/− mice display higher parasitemia levels." (PMID 20442858, 2010). "Importantly, Pc-infected iNOS-/-, TNFRΔLyz2 and HIF-1 α ΔLyz2 mice show impaired release of TNF and glycolysis in monocytes, along with increased parasitemia and disease tolerance." (PMID 41648113, 2026). "Here, we show that TNF signaling hampers physical activity, food intake, and energy expenditure while enhancing glucose uptake by the liver and spleen as well as controlling parasitemia in P." (PMID 41648113, 2026). "Our GO enrichment analysis shows that response to stimulus is the most significantly enriched biological process, which is highly consistent with host immune response mechanisms triggered by parasite infections, in which the core genes TNF, STAT3, STAT5A, PDGFB, ADRB2 and SMO were included." (PMID 41153368, 2025). "Our findings demonstrate that synovial parasitosis in osteoarthritic patients is not only influenced by host and therapeutic factors, such as corticosteroid use, but is also consistently associated with elevated inflammatory biomarkers (MMP-9 and TNF-α)." (PMID 41410796, 2025). "Among the promising findings, Pereira-Chiocolla and colleagues demonstrated the protective potential of immunizing mice with T. gondii-derived EVs, resulting in increased specific antibodies, elevated IFN-γ, IL-10, TNF-α, and IL-17 expression, reduced parasitemia, and higher survival rates." (PMID 40141288, 2025). "Additionally, increased parasitemia showed a close relationship with increased TNF and NO serum levels, an increase in TBARS and neurotransmitter levels in the brain cortex, and depressive-like behavior in the group of Veh-treated infected mice." (PMID 41237192, 2025). "However, it has become clear that TNF-α displays an outstanding position in the defense against viral, bacterial, and parasitic infections and also in the incitement of autoimmune responses." (PMID 39063004, 2024). "However,LV39 LPG stimulated a higher production of TNF-α in murine macrophages,suggesting a role for L. major LPGin driving inflammatory responses during parasite infection." (PMID 39313410, 2024). "Combined, these results support the hypothesis that the dynamic methylation changes taking place in the DMR result in changes in TNF gene expression levels that increase during symptomatic parasitemia and revert back to pre-infection levels." (PMID 37470040, 2023). "While increased TNFα levels were present from the first week of infection onwards and peaked after 4 weeks, INFγ levels peaked relatively early at 7dpi, following the development of the first parasitemia wave." (PMID 36420267, 2022). "The levels of IL-6 and IL-10 and the IL-10/TNF-α ratio were inversely associated with the age of the study participants in the absence of parasitic infections." (PMID 35421083, 2022). "Notably, previous studies have reported that the multifunctional Th1 cells simultaneously expressing IFN-γ, TNF-α and IL-2 correlated best with the degree of protection of vaccine models against parasite infection." (PMID 35812841, 2022). "brucei-challenged mice was unrelated to TNF-mediated parasitemia control." (PMID 34200074, 2021). "We therefore, infer that TNFα increase among others, may be one of the possible mechanisms responsible for the decreased percentage parasitemia at 400 mg/kg of DF." (PMID 33767260, 2021).
parasitemia (continued). "Likewise, IL-10 can inhibit the production of TNF-α and counteract detrimental biological effects on the overall state of the animal once the maximum peak of parasitemia has been surpassed, as reflected in the healthy appearance of C-TIM after parasitemia." (PMID 35059328, 2021). "The lower concentrations of TNF-α in this study cohort of children with parasitic infections may be due to their significantly higher concentrations of IL-10." (PMID 34539633, 2021). "Probably denoting that with increasing parasitemia, TNF-α as well as IL-6 may work synergistically to decrease parasitemia levels." (PMID 33281757, 2020). "An increased TNF-α level was in accordance with decreased parasitemia in the infected group." (PMID 32190083, 2020). "TNF can participate in parasite killing and, consequently, parasitemia reduction." (PMID 31871954, 2019). "Additionally, in a cerebral malaria model, Tnf mRNA was detected by in situ PCR in astrocytes, indicating that astrocytes are activated and respond by upregulating TNF production in different parasitic diseases." (PMID 28877735, 2017). "The balance in interleukin (IL)-10/TNF-α rate could prevent increased parasitemia and host pathology." (PMID 28243235, 2017). "The TNF-enriched inflammatory milieu created by T. cruzi infection of astrocytes may fuel parasite infection of these glial cells via TNF/TNFR1 signaling, thereby perpetuating the parasite cycle in the CNS." (PMID 28877735, 2017). "While the strength and significance of this relationship was less clear in the current study, it is supported by our previous finding that prevalence of asymptomatic parasite infection was reduced in 4-year-old children with high frequencies of Pf-specific TNFα-monofunctional CD4 T cells." (PMID 29097996, 2017). "However, at day 7 p.i., corresponding to the time when mice start to succumb to the parasitic infection, TRIM21-deficient mice exhibited significantly decreased levels of RANTES and TNFα; both are induced by the NF-κB-mediated signalling pathway." (PMID 28701773, 2017). "As TNF reduces parasitemia we have searched for a target that might be involved in the control of cell cycle proliferation." (PMID 27080559, 2016). "Using the Trypanosoma brucei brucei GVR35 experimental infection model, we demonstrate that systemic delivery of the counter-inflammatory cytokine IL-10 lowers plasma IFN-γ and TNF-α concentrations, CNS parasitosis and ameliorates neuro-inflammatory pathology and clinical symptoms of disease." (PMID 26505761, 2015). "OI promotes a severe acute disease, elevated parasitemia and TNF mediated mortality." (PMID 26090667, 2015). "Because TNF is critical to control parasitemia, etanercept administration started at 14 days post-infection, at the time that parasitemia could also be controlled by humoral response." (PMID 26090667, 2015). "We observed that deficiency on TNF-α and IL-18 secretion did not have impact on parasitemia and animal survival." (PMID 22509418, 2012). "In this regard, the depleting treatment in infected IL-17RA KO mice that per se presented reduced tissue neutrophil numbers further exacerbated the already exuberant IFN-γ and TNF secretion and worsened liver damage, resulting in wasting disease, higher parasitemia and increased mortality." (PMID 22577359, 2012). "Plasma concentrations of the soluble TNF-α receptors sTNFRI and sTNFRII, which bind to circulating TNF-α and regulate its activity, correlate positively with parasitemia and disease severity in P. falciparum malaria in Africa, but scant data are available for P. vivax infections." (PMID 22973442, 2012). "Since our vivax malaria patients have higher sTNFRII concentrations (which correlate positively with parasitemia) and sTNFRII/TNF-α ratios than falciparum malaria patients, they have comparatively less free TNF-α available for interaction with cell surface receptors." (PMID 22973442, 2012).
parasitemia (continued). "Thus, massive phagocytosis of trypanosomes (as seen during peak parasitemia) leads to hyper-activation of macrophages and increased production of monokines (IL-1, TNF-α, IL-6, IL-12, monocyte chemotactic protein-1 [MCP-1]) and the T-cell cytokine (IFN-γ)." (PMID 23144931, 2012). "TNFα is well known for its role in host defense against bacterial, viral and parasitic infections." (PMID 20463923, 2010). "Pressurized oxygen therapy reduced peripheral parasitemia, expression of TNF-α, IFN-γ and IL-10 mRNA levels and percentage of γδ and αβ CD4+ and CD8+ T lymphocytes sequestered in mice brains, thus resulting in a reduction of blood-brain barrier (BBB) dysfunction and hypothermia." (PMID 18769544, 2008). "Despite the significant presence of the proinflammatory cytokines IFN-γ and TNF-α, the expression of the anti-inflammatory cytokine IL-10 may contribute to a balance that promotes parasitemia control while protecting the animal from the inflammatory effects of Th1 cytokines." (PMID 40743218, 2025). "Third, due to financial constraints, we could only analyse three types of cytokines; exploring other cytokines, such as interleukin 6, interleukin 10and tumor necrosis factor α, could strengthen our understanding of the immune response to parasitic infections and malnutrition." (PMID 37111135, 2023). "In fact, in the later phases of infection, parasitemia and tissue parasitism were significantly reduced in 5-LO−/− mice and it is in accordance with previous studies showing that cytokines such as IL-1β, IL-6, IL-12, TNF-α, and IFN-γ play a relevant role in host killing mechanisms against T. cruzi." (PMID 25165415, 2014). "The innate target cells could be macrophages themselves (being infected by LCMV) which are modulated by IL-10 such that they would better sustain viral replication, potentially by inhibition of NO production as it was shown for parasite infection or by inhibition of TNF-α and IFN-γ production." (PMID 24244162, 2013). "Finally, high levels of TNF-α and NO mediated through IgE generation may also account for deleterious chronic inflammatory diseases that are observed during many parasitic infections." (PMID 21526166, 2011). "In vivo, CL Brener induced significantly higher parasitemia, cardiac parasite burden, and sustained proinflammatory cytokine expression (IFN-γ, TNF-α) compared to AQP-RE." (PMID 41394106, 2025). "Children with high parasite density (>10,000 parasites/μL) had higher plasma levels of TNF‐α (p < .001), IFN‐ɣ (p < .001), IL‐1β (p < .001), IL‐6 (p < .001), GM‐CSF (p < .001), and IL‐10 (p < .001) than those with low parasitemia." (PMID 39240033, 2024). "During the proliferation of merozoites inside erythrocytes, macrophages and NK cells secrete ROS, TNF-α, and INF-γ, possibly contributing to the decrease in parasitemia." (PMID 37104446, 2023). "As mentioned in studies, in the early stages of CE, a Th1 immune response dominates to protect from parasite infection by secreted IL-2, IFN-γ, TNF and so on." (PMID 35360110, 2022). "The pro-inflammatory cytokines TNF-α and IFN-γ are good indicators of the establishment of parasite infection in most apicomplexan protozoan infections, similar to what would be observed in Plasmodium spp." (PMID 34112218, 2021). "Upregulation of pro-inflammatory cytokines such as IFN-γ (IFNG), IL12, and TNF-α (TNF) during the early stages of infection contributes to protection and resolution of parasite infection." (PMID 33123155, 2020). "In trypanotolerant models a strong, early pro-inflammatory immune response involving IFN-γ, TNF and NO, combined with a strong humoral anti-VSG response, ensures early parasitemia control." (PMID 32012211, 2020). "For example, patients with moderate parasitemia in endemic regions of Colombia were shown with cellular immune responses including high IFN-γ and TNF-α levels and a pro-inflammatory cytokine profile in unstable transmission regions." (PMID 33374596, 2020).
parasitemia (continued). "Although the cytokines (IL-1β, IL-4, IL-6, IL-12, TNF-α, and IFN-γ) were increased in all groups after the parasite infection, the cytokine levels of the group immunized with SAG1-VLPs were markedly reduced compared to the non-immunized infection group." (PMID 32325746, 2020). "To further investigate the requirements for sustained cellular immunity to an intracellular parasitic infection, we assayed the contribution of CD4+ and CD8+ T cells to the production of IFN-γ, TNF-α and IL-10 in spleen cells of post-challenged animals." (PMID 31739549, 2019). "Patients having moderate parasitemia in endemic regions of Colombia have high IFN-γ and TNF-α levels, a pro-inflammatory cytokine profile correlated with the response found in an unstable transmission region." (PMID 28243235, 2017). "The IL-17 is related to protection, and high levels of this interleukin result in decreased parasitemia and increased production of inflammatory cytokines such as IFN-γ, IL-6 and TNF-α." (PMID 29255475, 2017). "Secretion of pro-inflammatory cytokines during N. caninum infection, such as IL-12, TNF-α, and IFN-γ, is necessary for control of parasite infection by host immune system." (PMID 28798732, 2017). "Serum IgG and cytokines (TNF-α and IFN-γ) levels in culture supernatant were measred by ELISA.Survivorship and parasitemia were daily monitored for 21 days." (PMID 28883981, 2017). "At the time of acute illness (day 1), subjects had upregulation of innate immune response, cytokine, and inflammation-related genes (IL-1β, IL-6, TNF, and IFN-γ), which was more frequent with parasitemias >100,000 per μL and body temperatures ≥39°C." (PMID 26491700, 2015). "They differentiate into inflammatory macrophages and dendritic cells (DCs) that produce tumor necrosis factor (TNF), inducible nitric oxide synthase, and reactive oxygen species in response to bacterial and parasitic infection and can stimulate naive T cells." (PMID 23582326, 2013). "Here we analyzed the requirement of TLR2 and TLR9 in the release of TNF-α, IL-12/IL-23p40 and IFN-γ, all present before the peak of parasitemia." (PMID 23650544, 2013). "We showed that adoptive transfer of highly enriched naïve CD4+CD25+ T cells (Tregs) led to increased peak parasitemia and production of disease exacerbating inflammatory cytokines, including IFN-γ, IL-6, TNF and MCP-1 early during infection in C57BL/6 mice." (PMID 22860150, 2012). "phox KO mice had similar parasitemia, similar tissue parasitism and similar levels of IFN-γ and TNF in serum and spleen cell culture supernatants, when compared to wild-type controls." (PMID 22348160, 2012). "In our study, malaria infections were shown to significantly decrease the frequency of CD4 and CD8 triple positive MFT cells expressing IFN-γ, TNF-α, and IL-2 in lung cells of BCG vaccinated mice when high levels of parasitemia were present." (PMID 22205939, 2011). "In parasitic infections, high levels of RNS may cause: oxidative damage of DNA (leading to mutations and strand brakes); inhibition of DNA repair and synthesis; inhibition of protein synthesis; inhibition of mitochondrial activity; down- or up-regulation of cytokine (e.g. TNF-α) levels." (PMID 21408620, 2011). "We also evaluated the contribution of TLR4 to the in vivo control of parasitemia levels and survival, as well as to IFN-γ and TNF-α production in the B6 and B10 backgrounds." (PMID 20442858, 2010). "However, parasitic infections disrupted the inflammatory balance within the placenta, leading to increased levels of IFN-γ and TNF-α, which adversely affected pregnancy." (PMID 40007749, 2025). "Parasitemia was determined by the Brener method and relative gene expression (RGE) of six cytokines was evaluated by RT-qPCR to determine the Th1 response (IFN-γ, TNF-α, IL-1β, IL-12) and the Th2 response (IL-4 and IL-10)." (PMID 40743218, 2025).